STAT3 (signal transducer and activator of transcription 3)
Diseases named in the same sentence as STAT3 in open-access papers (continued):
Sharing a sentence is not in itself a finding about the gene and the disease.
tumor (continued). "One of the different STAT3-dependent oncogenic functions is an activation of DNA-methyltransferases (DNMTs), which may lead to the epigenetic silencing of tumor suppressor genes by gene promoter methylation." (PMID 31052302, 2019). "Moreover, STAT3 inhibition would help activate anti-tumor immunity by reducing immunosuppressive factors and increasing the infiltration of immune cells into the TME." (PMID 31684144, 2019). "Interestingly in HCC models, liver specific STAT5 knockout results in tumor formation through the enhanced activation of TGFβ/STAT3 signaling." (PMID 31684144, 2019). "The survival effect of Stat3 may be the reason for the resistance of tumor cells to chemotherapeutic drugs and targeted therapies when grown to high but not low densities in culture." (PMID 30717267, 2019). "With respect to the role of STAT3 in solid tumors, constitutive activation is common but it remains unclear if this is a specific driver of tumor growth or if they are secondary to other changes such as upstream cytokine signaling." (PMID 31409327, 2019). "Looking to the future, while the role of STAT3 has been established in cancer biology, identifying tumor biomarkers that can indicate patient sensitivity to STAT3 inhibition and expansion of target inhibition to other aberrant transcription factors will be important." (PMID 31671769, 2019). "Similarly, SOCS3 downregulation allows for persistence of STAT3 mediated signaling that is proposed to contribute to carcinogenesis by inducing multiple tumor-promoting genes." (PMID 30859089, 2019). "Moreover, increased epithelial STAT3 activity correlates with decreased survival and advanced tumor stage in PDA patients." (PMID 31609088, 2019). "Moreover, progranulin knockdown reduces STAT3 phosphorylation and cell proliferation induced by tumor‐infiltrating leukocyte (TIL)‐derived supernatants in CRC cell lines and human CRC explants." (PMID 31361391, 2019). "Aside from the activation of ERK and Blimp-1, a further—not necessarily directly associated— driver of tumor progression is STAT3." (PMID 31540511, 2019). "However, abnormal expression of STAT3 leads to its constitutive activation, which promotes malignant transformation and tumor progression through oncogenic gene expression in numerous human cancers." (PMID 31861597, 2019). "We found EMT and STAT3 scores to be increased in the tumor and its derived BTSC upon recurrence." (PMID 31652994, 2019). "Further analysis revealed that Lkb1 loss induces interleukin- (IL-) 11 expression in gastric fibroblasts and subsequent activation of the Janus Kinase/Signal Transducer and Activator of Transcription 3 (JAK/STAT3) pathway in tumor epithelia, promoting GI tumorigenesis." (PMID 31885581, 2019). "However, downregulation of IL-6R by siRNA did not induce miR-34a expression in the HGSC cell line, A2780, suggesting that IL-6R/STAT3/miR-34a feedback is tumor specific." (PMID 31448054, 2019). "Since IL‐11 can activate STAT3 signaling and promote malignant phenotypes during tumor progression, we therefore reasoned that IL‐11 might be the mediator used by OLC8 to regulate STAT3 signaling." (PMID 31273847, 2019). "Because STAT3 mediates distinct biological effects by interacting with specific cooperating proteins, the identification of tumor‐specific STAT3 cofactors could facilitate the development of compounds that interfere exclusively with STAT3 in cancer cells." (PMID 31361391, 2019). "In addition, PHB1 has a strong anti-tumour and anti-inflammatory effect via blocking NF-κB and STAT3 signalling pathway." (PMID 30886235, 2019). "Previous studies have shown that the expression of HK2 could be regulated by STAT3 in tumor cells such as MCF7, HepG2, and A549 cells." (PMID 30952834, 2019). "The IL6/STAT3 signaling pathway has been extensively explored in tumor progression." (PMID 31486564, 2019).
tumor (continued). "Furthermore, we investigated the contribution of IL-6, IL-8 and the JAK2/STAT3 signaling pathway to the pro-tumor effect of GC-MSC-primed macrophages." (PMID 31801938, 2019). "As STAT3 is a well-known transcriptional factor in regulating tumor metastasis, we further investigate whether B7-H6 promotes tumor invasion and metastasis via STAT3 activation." (PMID 30609841, 2019). "Therefore, clinical approaches should consider including a Stat3 inhibitor in the therapeutic protocol in order to improve tumour response to radiotherapy and chemotherapy." (PMID 31690341, 2019). "Having greater STAT1 than STAT3 signaling can promote anti-tumor immune responses." (PMID 31681561, 2019). "Peripheral and tumor-associated NK cells in STAT3-targeted tumor-bearing mice, exhibit higher expression of the NK activation markers NKG2D, CD69, Fas ligand (FasL), granzyme B, perforin, and IFNγ, resulting in reduced tumor growth and enhanced survival." (PMID 31057536, 2019). "Furthermore, in vivo experiments showed inhibition of STAT3-mediated tumorigenesis, angiogenesis, and tumor growth in xenograft mouse models of prostate and hepatocellular carcinoma." (PMID 31671769, 2019). "In addition to anti-BTLA Ab, chemotherapy combined with other BTLA-related inhibitors such as LY294002 (AKT inhibitor) or BP-1-102 (STAT3 inhibitor) can generate potent anti-tumor effects compared to chemotherapy alone." (PMID 31753019, 2019). "Taken together, the present study confirmed that YPFS inhibited angiogenesis and tumor growth in mice bearing HCC, which may be associated with the attenuation of the TSLP/STAT3 signaling pathway." (PMID 31885639, 2019). "Importantly, STAT3 activation has also been found to contribute to the immunosuppressive tumor microenvironment by prohibiting tumor cell apoptosis and promoting tumor growth and metastasis." (PMID 31565097, 2019). "Likewise, STAT3 activation induces IL-6 gene transcription and, thus, establishes a feedback loop in tumor tissues." (PMID 31695609, 2019). "The inhibition of STAT3 signaling in either macrophages or bone marrow-derived DCs is of great importance in cancer immunotherapy, because it allows these APCs to restore the responsiveness of tolerant T-cells from tumor-bearing mice." (PMID 31480382, 2019). "The immunohistochemistry results showed that the intensity of E-cadherin-positive cells was significantly increased, whereas the intensity for p65 and STAT3-positive cells were relatively decreased in the tumor tissue of the MDA-MB-231-IL-32θ group compared to that of the MDA-MB-231-EV group." (PMID 31126309, 2019). "Furthermore, p-STAT3 packaged by exosomes from RKO/R cells increased resistance of tumor cells to 5-FU in vivo." (PMID 31324203, 2019). "Lactate, the end-product of the anaerobic glucose catabolism, can be released from the cancer cell and activates the ERK1/2 and STAT3 signalling in monocytes, promoting their polarization in pro-tumor M2-polarized TAMs and favoring cancer cell proliferation and migration." (PMID 31117237, 2019). "Depletion of Stat3 drastically inhibited tumor sphere formation in these cells." (PMID 30614183, 2019). "In thyroid, STAT3 pathway was found to be involved in the onset and invasion of tumor." (PMID 31921695, 2019). "While STAT3 is phosphorylated in 60% of human HCC and active STAT3 correlates with tumor aggressiveness, no patients harboring STAT3 mutations have been described." (PMID 31683891, 2019). "Activation of STAT3, an important transcription factor that regulates the expression of survivin, MMPs, and other proteins, has been observed in many tumors and is closely related to tumor cell survival and proliferation." (PMID 31354472, 2019). "Moreover, embelin has been observed to suppress tumor growth through interleukin 6/STAT3 signaling in various cancer types, and can also inhibit tumor metastasis." (PMID 31635287, 2019). "Along this line, STAT3 inhibition frequently resulted in impaired tumor growth." (PMID 31653043, 2019).
tumor (continued). "STAT3, which is a central regulator of cancer cell proliferation and invasion, is activated by cytokines and growth factors via tyrosine phosphorylation (dimerization), and nuclear translocation in tumor cells." (PMID 31028131, 2019). "STAT3 is frequently hyper-activated in tumor cells and regulates the expression of oncogenic genes." (PMID 30871017, 2019). "Furthermore, increased IL-6 stimulates the activation of JAK/STAT3 signaling, functioning as transcriptional activators of STAT3 mediated target genes, which results in tumor proliferation, and/or survival." (PMID 31817563, 2019). "STAT3 levels of CD19+ Tim‐1+ cells were checked in tumour‐bearing KO and WT mice." (PMID 30467955, 2019). "The suppression of the oncogene Signal Transducer and Activator of Transcription 3 (STAT3) appears to play a key role in tumor growth inhibition, although alternative mechanisms may also contribute." (PMID 31091784, 2019). "Indeed, ACVR1 mutant tumor tissue had significantly increased phosphorylated STAT3 Y705 levels as compared to their normal brain tissue counterparts." (PMID 30833574, 2019). "Finally, we show both in tumor tissue and in cell lines that Stat3 supports SHH signaling which is potentiated by co-treatment with the STAT3 activating cytokine IL-6." (PMID 31683879, 2019). "Furthermore, STAT3 activation reduces tumor cell sensitivity for NK-mediated killing via alteration of NK-activating ligands such as NKG2D." (PMID 31658669, 2019). "could ameliorate tumor metastasis in the lung metastasis model by inhibiting Stat3 signal pathway and increasing CD8+T cells." (PMID 31649548, 2019). "Secretion of IL-6 by tumor cells and tumor microenvironment cells contributes to STAT3 activation." (PMID 31695609, 2019). "Interestingly, this study also indicated that a stable fraction of Stat3 protein remained present in the tumor cells that cannot be depleted using their approach, whereas reduction of Stat3 phosphorylation was very well possible." (PMID 30857197, 2019). "NF-kB and STAT3 signaling pathways provoke tumor-stimulating reactions by the production of interleukin-6 (a well-known growth factor for myelomatous plasma cells), prostaglandin E2, matrix metalloproteinases, and RAGE stimulation in the microenvironment of a tumor." (PMID 30836666, 2019). "Moreover, it is possible that dysregulated JAK/STAT3 signaling has its greatest impact within the context of tumor promotion through modulation of the local microenvironment." (PMID 31409327, 2019). "And STAT3 protein is central in determining whether immune response promotes or inhibits cancer in the tumor microenvironment." (PMID 31028131, 2019). "Estrogenic GPER signaling may contribute to the regulation of several genes in tumor cells via diverse transcription factors as well as the involvement of STAT3." (PMID 30728047, 2019). "Furthermore, we investigated the relationship between PD-L1 and p-STAT3 expression in tumor samples from patients with NSCLC using IHC, as well as their relationship to patient survival." (PMID 31511071, 2019). "Sunitinib, which blocks multiple tumor-associated tyrosine kinases, enhances antitumor effects by blocking immune system STAT3, decreasing the numbers and effectiveness of myeloid-derived suppressor and Treg cells and affecting the tumor immunologic microenvironment." (PMID 32257917, 2019). "During this calculation, we adjusted STAT3 activity inference scores for tumor purity." (PMID 31796877, 2019). "NF-κB1 and STAT3 are crucial factors regulating the tumor microenvironment." (PMID 31396300, 2019). "STAT3 inhibition was shown to upregulate immune checkpoints such as cytotoxic T lymphocyte associated protein 4 (CTLA-4) and programmed cell death protein 1 (PD-1) to enhance anti-tumor immune responses." (PMID 31698775, 2019). "Similarly, there is also a positive feedback loop between cytokine release and the activation of STAT3, and STAT3 is required for tumor transformation." (PMID 31396300, 2019).
tumor (continued). "Moreover, genetic and pharmacological inhibition of STAT3 resulted in impaired viability of tumor cells and reduced outgrowth of brain metastasis." (PMID 31396225, 2019). "We therefore speculated that CARD may exert its anti-tumor activity by regulating the STAT3 signaling pathway." (PMID 31028131, 2019). "The IL-6/STAT3 pathway facilitates the expansion of immunosuppressive cells or changes the balance of T cell subsets, such as T regulatory cells and MDSCs, which promote tumor growth." (PMID 31640814, 2019). "Interestingly, tumor-derived exosomes harboring HSP70 were found to mediate the suppressive activity of the myeloid-derived suppressor cells via activation of STAT3 and ERK." (PMID 31861612, 2019). "Several reports have indicated that activated STAT3 modulates the expression of several target genes involved in cell cycle regulation, angiogenesis, tumor invasiveness and apoptosis, and that the disruption of STAT3 in myeloid cells alters immunosuppressive cell abundance." (PMID 30979375, 2019). "Constitutive activation of STAT3 is involved in a variety of tumor cells." (PMID 31035454, 2019). "Thus, we tested antibodies specific to these phosphorylated residues and found highly increased STAT3 phosphorylation of both residues in DFTD tumor cells compared with fibroblasts." (PMID 30645971, 2019). "However, ablation of STAT3 in the later stage of tumor progression significantly increased the invasiveness of the tumors and decreased the survival of the animals (i.e., tumor suppressor role)." (PMID 31072360, 2019). "Metastasizing cancer cells, irrespective of their origin, were shown to induce a Stat3 dependent pro-tumorigenic program in a subset of tumor-associated reactive astrocytes." (PMID 31632393, 2019). "Curcumin could also reduce tumor spheres of NCI-H460 cells by inhibiting the JAK2/STAT3 signaling pathway in both in vitro as well as in vivo." (PMID 31817718, 2019). "Increased secretion of IL-6 in the tumour microenvironment, promotes tumourigenesis by activation of the signal transducer and activator of transcription 3 (STAT3) and expression of its target genes involved with apoptosis, survival, proliferation, angiogenesis, invasiveness and metastasis." (PMID 31383893, 2019). "Interestingly, acetylation of STAT3 also induces tumor progression through enhanced pro-tumorigenic IL-17A secretion." (PMID 31684144, 2019). "However, addition of exogenous IL6 to tumor cell culture can restore STAT3 signal transduction and increase VEGF expression." (PMID 31355138, 2019). "In addition, Cucurbitacin I, a triterpenoid that acts as a potent inhibitor of the STAT3/JAK has been shown to exert anti-tumor effect in NB." (PMID 31867574, 2019). "In breast cancer, garcinol was shown to inhibit STAT3-NF-kB signaling, resulting in reduced invasiveness, in vitro, and significantly attenuated tumor growth in NOD-SCID mice; thus, building a case for the preclinical investigation of the probable anti-GBM effect of garcinol in this stance." (PMID 31783691, 2019). "In addition, hypoxia increased miR-103a levels in the exosomes of lung cancer cells and patients, modifying M2 macrophage phenotype through AKT and STAT3 activation with a stimulatory effect on tumor progression and angiogenesis." (PMID 31242686, 2019). "To examine whether our in vitro findings on the involvement of BA on PI3K/AKT and STAT3 signaling would also hold true in vivo, we investigated the protein expression of key members of the two signaling pathways in tumor lysates from brevilin-A-treated mice." (PMID 31178739, 2019). "Furthermore, another observation of our study is the preferred localization of Stat3 positive cells at the nuclear level of tumour cells in the perinecrotic areas and at the tumour invasion front." (PMID 31690341, 2019). "The supportive influence of STAT3 to tumor angiogenesis was described in several malignancies." (PMID 31234597, 2019).
tumor (continued). "STAT3 contributes to tumour immune evasion through the accumulation and activation of tolerogenic dendritic and Treg cells, as well as the upregulation of immune checkpoint proteins such as CTLA-4, programmed cell death protein 1 (PD-1), and programmed death ligand 1 (PD-L1)." (PMID 30876435, 2019). "In addition, while environmental-STAT3 is most influential at the primary site, tumor-derived STAT3 seems to be dominant at metastatic sites where its activity persists." (PMID 31796877, 2019). "microRNA-34a (miR-34a) has been shown to be a key regulator of tumor suppression by targeting several cancer-related signals, including the interleukin-6 receptor (IL-6R)/Signal Transducers and Activator of Transcription 3 (STAT3) signaling pathway." (PMID 31448054, 2019). "Furthermore, we found that there was a reverse trend of ERK-mediated STAT3 activation in response to the alteration of SAP18 expression under tumor conditions." (PMID 31395859, 2019). "Thus, this is a new feed forward mechanism that explains the persistent STAT3 activation in cancer cells and the tumor microenvironment, which is important for malignant tumor progression and metastasis." (PMID 31534132, 2019). "Therefore, we propose balancing pro-tumor STAT3 activation with anti-tumor STAT1/STAT2 activation as a novel therapeutic approach." (PMID 31684144, 2019). "These experiments indicate that CARD9 signaling in the immune environment of developing colorectal cancers can trigger the tumor-promoting STAT3 pathway within tumor cells, presumably via ILC-mediated IL-22 production, comparable to its role during epithelial regeneration after acute colitis." (PMID 30906296, 2019). "The activation of STAT3 induces oncogenic transformation in cells and tumor formation in nude mice." (PMID 31484165, 2019). "As the key signal pathway connecting inflammation and tumor, activated signal transduction and transcriptional activation factor 3 (STAT3) leads togenetic abnormal expression, gene silencing, genomic instability, etc. in tumor cells, and induces therapeutic resistance." (PMID 31315785, 2019). "However, tumors were significantly smaller which correlated with a reduced BrdU incorporation and reduced Stat3 activation in tumor epithelia." (PMID 30353167, 2019). "STAT3 is a transcription factor for S1PR1 and, simultaneously, enhanced S1PR1 expression activates STAT3 and upregulates IL-6 expression, a proinflammatory cytokine crucial for STAT3 activation and inflammatory cell-mediated transformation and tumor progression." (PMID 31534132, 2019). "Treatment of ALK− ALCL tumor bearing mice carrying JAK1 and STAT3 mutations with ruxolitinib, a JAK1/JAK2 inhibitor, led to inhibition of tumor formation, which demonstrates the therapeutic potential of targeting the JAK1/STAT3 pathway." (PMID 31684088, 2019). "Their findings contrastingly indicate that STAT3 functions as a tumor suppressor in both models." (PMID 32039025, 2019). "In addition, we further performed immunohistochemical staining of MMP-9 and STAT3 in HCC tumor specimens." (PMID 30609841, 2019). "In addition to SOCS-1, the induction of signal transducer and activator of transcription 3 (STAT-3) in DCs by tumour-derived factors renders DCs tolerogenic and suppresses their antitumour potency." (PMID 30717461, 2019). "IL-6 is closely correlated with STAT3, and STAT3 plays a key role in cell proliferation and differentiation, so IL-6 can not only promote the development of inflammation but also accelerate the proliferation of normal cells and tumour cells." (PMID 30956980, 2019). "In addition, the effect of STAT3 inhibition on tumor cell proliferation was monitored by BrdU incorporation after IL6 stimulation." (PMID 31438567, 2019).